BNIP3 (BCL2 interacting protein 3)
Diseases named in the same sentence as BNIP3 in open-access papers (continued):
Sharing a sentence is not in itself a finding about the gene and the disease.
melanoma (32 papers, 2012 to 2025). A malignant, usually aggressive tumor composed of atypical, neoplastic melanocytes. "As a mitophagy receptor, upregulation of BNIP3 was associated with poorer melanoma patient’s endpoint, and BNIP3 knockout in melanoma cells inhibited tumor growth in vivo." (PMID 37056778, 2023). "In this regard, loss of BNIP3 has been shown to cause the polymerization of actin into bundles (stress fibres) and to increase F-actin staining in melanoma cells." (PMID 38011286, 2023). "In this paper, BNIP3-melanoma cells display increased intracellular Fe(II) levels, caused by an elevated, NCOA4-mediated ferritinophagy, the latter fostering PHD2-mediated HIF-1α destabilization." (PMID 35682788, 2022). "Knockdown of baseline BNIP3 in melanoma cells caused accumulation of actin stress fibers and membrane ruffles and induced aberrations in cytoskeletal structures." (PMID 34568319, 2021). "In conclusion, we found that melanoma cell-associated BNIP3 played a highly contextual immunomodulatory role at the melanoma-immune cell interface." (PMID 29707136, 2018). "In line with this, prophylactic vaccination experiments showed that the loss of BNIP3 tends to increase the intrinsic resistance of B16-F10 melanoma cells to ICD-associated anticancer vaccination effect in vivo." (PMID 29707136, 2018). "In line with this, increased BNIP3 levels in melanoma patients appear to be linked with poor prognosis." (PMID 29312568, 2017). "This suggests that blocking autophagy may induce beneficial immune response, although it has been demonstrated that loss of BNIP3 significantly reduced phagocytic clearance of melanoma cells undergoing cell death." (PMID 32340261, 2020). "Moreover, the aggressive melanoma cell phenotype driven by BNIP3 is associated with glutamine metabolism in melanoma cells." (PMID 30866509, 2019). "Thus, normoxic vs. hypoxic and live vs. dying cell contexts influence the ultimate immunomodulatory roles of melanoma cell-associated BNIP3." (PMID 29707136, 2018). "In order to systematically decipher the role of cancer cell-associated BNIP3 in regulating the melanoma-immune cell interface, we knocked-down the overall expression of BNIP3 via the shRNA methodology (BNIP3KD), in the well-established murine B16-F10 melanoma cells." (PMID 29707136, 2018). "We also evaluated whether melanoma-associated BNIP3 affects crucial determinants of chemotherapy-induced ICD such as danger signals and in vivo anticancer vaccination effect." (PMID 29707136, 2018). "However, whether melanoma-associated BNIP3 modulates CD47-associated immunological effects or ICD has not been explored properly." (PMID 29707136, 2018). "However, BNIP3 proficient or deficient melanoma cells injected into the transgenic zebrafish larvae expressing mCherry+macrophages (fms:nfsB.mCherry; to analyse localized chemotaxis close to injection site via intra-vital microscopy), also failed to recruit the macrophages (data not shown)." (PMID 29707136, 2018). "BNIP3 deficiency induces NCOA4-mediated ferritinophagy, with PHD2-mediated HIF-1α downregulation inhibiting tumor glycolysis and growth in BNIP3-silenced melanoma cells." (PMID 41298345, 2025). "In melanoma and other cancers, BNIP3 and P4HA1 are induced under hypoxic conditions, promoting tumor growth and progression." (PMID 41000875, 2025). "The BNIP3 gene was found to have the highest expression level (4.76-fold) in A-375 melanoma cells in response to UA treatment." (PMID 39473730, 2024). "Glutamine has been demonstrated to increase hypoxia-inducible factor-1 (HIF1) expression and also increase the pro-autophagic function of BNIP3 (Bcl2/adenovirus E1B interacting protein 3), thus encouraging melanoma cell dissemination." (PMID 37384249, 2023).
melanoma (continued). "Maes and colleagues showed that in B16F10 melanoma cells BNIP-3 determines aggressive behavior and migration: downregulation of BNIP-3 prevented clonogenic growth, caused an increase of cellular ROS levels and led to alteration of the mitochondrial network." (PMID 36539400, 2022). "BNIP3 is a protein that interacts with the antiapoptotic protein Bcl-2, and it is showed that BNIP3 drives the migration and invasion of melanoma cells and promotes angiogenesis by regulating integrin-related proteins." (PMID 35783530, 2022). "BNIP3 plays a pro-tumorigenic role by driving aggressive features in melanoma cells, including migration, clonal growth, cell survival, and vasculogenic mimicry." (PMID 34568319, 2021). "Deletion of Bnip3 decreases the formation of lamellipodia and filopodia, and the migratory ability of melanoma cells." (PMID 33004792, 2020). "Increased level of BNIP3 accompanying activation of autophagy was correlated with poor efficacy of pembrolizumab in melanoma patients." (PMID 32340261, 2020). "On the other hand, in response to ICD, BNIP3 accentuated ATP secretion, phagocytic clearance and the vaccination potential of the dying melanoma cells." (PMID 29707136, 2018). "To this end, we evaluated the impact of the genetic ablation of BNIP3 (i.e. BNIP3KD) in melanoma cells, on macrophage-based phagocytosis, polarization and chemotaxis." (PMID 29707136, 2018). "We previously reported that in melanoma cells, BNIP3 regulates cellular morphology, mitochondrial clearance, cellular viability and maintains protein expression of CD47, a pro-cancerous, immunosuppressive 'don't eat me' signal." (PMID 29707136, 2018). "In conclusion, B16-F10 melanoma cells have an intrinsic ICD-resistant phenotype that is further potentiated by ablation of BNIP3 thereby advocating a partial pro-ICD role for BNIP3." (PMID 29707136, 2018). "We recently found that BNIP3, which is expressed at baseline levels in melanoma cells under normoxia and is further stimulated by hypoxia, serves critical pro-melanoma functions." (PMID 29707136, 2018). "To understand the impact of this interplay between BNIP3-hypoxia-CD47 on the phagocytic clearance of melanoma cells by macrophages, we performed in vitro phagocytosis experiments." (PMID 29707136, 2018). "On one hand, in living melanoma cells BNIP3 seemed to affect immunomodulatory responses elicited by hypoxia signalling." (PMID 29707136, 2018). "Henceforth, we decided to study the effects of BNIP3 on chemotherapy-based ICD induction in B16-F10 melanoma cells." (PMID 29707136, 2018). "Ablation of BNIP3 induces structural changes in the adhesion properties of melanoma cells and a strong reorganization of the actin filaments." (PMID 27929542, 2016). "Noticeably, upon CDH6 silencing we observed a phenotype similar to the one showed by BNIP3 silenced melanoma cells." (PMID 27929542, 2016). "Bnip3 is highly up-regulated in hypoxia and contributes to the organization and dynamics of the cytoskeleton and focal adhesion complexes, regulating migration of melanoma cells and vasculogenic mimicry." (PMID 39457009, 2024). "BNIP3 can increase melanoma cells’ migration and invasion ability." (PMID 36675706, 2022). "Elevated autophagy accompanying melanoma progression has been associated with loss of galectin-3, increased levels of sirtuin 1 (SIRT1), SIRT6, BNIP3, and long non-coding RNA ZNNT1, and enhanced activity of signaling pathways such as AKT, independent of the mutational status of BRAF." (PMID 32340261, 2020). "Indeed, BNIP3-silenced melanoma cells resulted in re-organization of focal adhesion sites and repressed cell–cell interaction." (PMID 31126310, 2019). "In line with this, silencing of BNIP3 in melanoma cells blunts glutamine-mediated effects on melanoma cell growth, migration and bioenergetics, suggesting that BNIP3 is vital to maintain mitochondria fitness required for glutamine-driven melanoma aggressiveness." (PMID 31121959, 2019).
melanoma (continued). "In general, we found that BNIP3 modulates melanoma cell-immune cell intersection in a highly contextual fashion and in a manner contingent upon the plasticity and immunoevasive character of the melanoma cells." (PMID 29707136, 2018). "In this study, we aimed to evaluate the impact of BNIP3 ablation in melanoma cells, on the interface with immune cells on various levels particularly, phagocytosis, chemotaxis and functional polarization (all three for macrophages), as well as susceptibility to ICD." (PMID 29707136, 2018). "Hence, we believe that future studies should strive to reveal the full relevance of BNIP3 using appropriate melanoma mice models recapitulating the hypoxic tumour microenvironment." (PMID 29707136, 2018). "Interestingly, BNIP3 ablation in melanoma cells profoundly reduced (**p = 0.0035) the secretion of ATP, without significantly affecting the emission of the other two danger signals." (PMID 29707136, 2018). "Therefore, the present study unveils that POMC therapy induces the activation of autophagic and apoptotic cell death pathways in melanoma cells through α-MSH/HIF-1α/BNIP3 signaling." (PMID 30062060, 2018). "Therefore, the present study unveiled a unique function of autophagy in promoting cell death during POMC-mediated melanoma suppression via α-MSH/HIF-1α/BNIP3/BNIP3L signaling pathway." (PMID 30062060, 2018). "Hence in this study, we evaluated the impact of the genetic ablation of BNIP3 in melanoma cells on the most foundational immunological processes like phagocytosis and chemotactic recruitment, both in vitro and in vivo." (PMID 29707136, 2018). "Indeed, genetic ablation of BNIP3 in B16-F10 melanoma cells in vitro had severe consequences for actin-based cytoskeletal architecture, cellular morphology, mitochondrial clearance and viability." (PMID 29707136, 2018). "On the other hand, our finding is consistent with previous studies, BNIP3 is required to maintain steady-state levels of intracellular complexes orchestrating the plasticity of the actin cytoskeleton, knockdown of BNIP3 could enhance melanoma cell migration." (PMID 28195146, 2017). "In melanoma cells, BNIP3 not only regulates autophagic clearance of ROS-generating mitochondria but is also a key orchestrator of actin-driven formation of PM protrusions (ruffles), melanoma cell morphology, and migration." (PMID 27896217, 2016). "Furthermore BNIP3 was found in melanoma to drive metabolic reprogramming of cancer cells by enhancing oxidative phosphorylation and inhibiting glycolysis thereby promoting melanoma invasion." (PMID 40438322, 2025). "Moreover, when exposed to the ICD inducer mitoxantrone, the loss of melanoma cell-associated BNIP3 did not alter apoptosis induction, but significantly prevented ATP secretion and reduced phagocytic clearance of dying cells." (PMID 29707136, 2018). "Interestingly, loss of BNIP3 reduced the expression of CD47 both in normoxic and hypoxic conditions while macrophage phagocytosis and chemotaxis were accentuated only when BNIP3KD melanoma cells were exposed to hypoxia." (PMID 29707136, 2018). "Notably, our analysis in melanoma patients also unravelled a positive correlation between CD47 and BNIP3 transcript levels, suggesting that the hypoxia-responsive protein BNIP3 may be a modulator of the phagocytic barrier in melanoma cells." (PMID 29707136, 2018). "Besides, legume lectin, ConA, could induce caspase-dependent apoptosis in human melanoma A375 cells, as well as BNIP3-mediated mitochondrial autophagy in HepG2 cells." (PMID 24992302, 2014). "Glutamine can increase the expression of hypoxia-inducible factor (HIF)-1α, enhance the pro-autophagic effect of its target BNIP3 (BCL2/adenovirus E1B 19kDa interacting protein 3), and promote the metastasis of melanoma cells." (PMID 32547948, 2020).
melanoma (continued). "As expected, by quantitative real-time PCR analysis, it was demonstrated that α-MSH significantly increased the gene expression of BNIP3 and BNIP3L in B16-F10 melanoma cells exposed to hypoxic condition." (PMID 30062060, 2018). "We identified a gene expression signature, and discuss the putative prognostic and predictive potential of BNIP3 and GBE1 genes in the clinical outcome of melanoma patients treated with anti-PD1 (pembrolizumab)." (PMID 29312568, 2017). "The loss of BCL2-interacting protein 3 (BNIP3, an inducer of autophagy) in melanoma cells did not alter apoptosis induction but attenuated the phagocytosis-mediated clearance of dying melanoma cells." (PMID 38336727, 2024). "Finally, it was delineated that α-MSH stimulated the HIF-1α signaling as well as the expression of BNIP3/BNIP3L, thereby promoting the autophagy and apoptosis in melanoma cells." (PMID 30062060, 2018). "Because of the Bcl-2 family such as BNIP3 and BNIP3L were triggered by HIF-1α in autophagic process, we next evaluated whether α-MSH modulated the Bcl-2 family gene expression in melanoma cells during hypoxia." (PMID 30062060, 2018). "This suggests that BNIP3 presence does not affect the ability of living melanoma cells to recruit these innate immune cells, at least in these in vivo settings." (PMID 29707136, 2018). "We could demonstrate that the levels of BNIP3 and GBE1 correlate with the clinical response in melanoma patients treated with anti-PD1." (PMID 29312568, 2017). "Interestingly, knock-down of HIF1α in SBcl2 melanoma cells diminished VEGF and BNIP3 mRNA induction by hypoxia, although to a lesser extent than observed in melanocytes." (PMID 22457728, 2012). "Lack of BNIP3 in melanoma cells induced increases in intracellular iron levels." (PMID 38389491, 2024). "Besides, some studies have documented that a lack of BNIP3 in melanoma cells can lead to increased intracellular iron levels, ROS depletion and peroxidative stress attributed to hyperactivation of NOCA4‐mediated ferritinophagy." (PMID 38389491, 2024). "Thus, B16-F10 melanoma-specific BNIP3 ablation in combination with hypoxia, stimulates phagocytic clearance of melanoma cells by macrophages, although this does not inversely correlate with the ecto-CD47 levels." (PMID 29707136, 2018).
lung cancer (26 papers, 2010 to 2025). A malignant neoplasm involving the lung. "Here, we summarized current knowledge about the BNIP3 gene and protein features and their role in cancer progression, especially in lung cancer in order to develop new therapeutic approaches associated with BNIP3." (PMID 33207677, 2020). "In other cases, including endometrial, breast, and lung cancers, high BNIP3 expression is associated with poorer prognosis and a more aggressive phenotype." (PMID 26102349, 2015). "BNIP3 has also been upregulated in lung cancer and is associated with poor prognosis." (PMID 34616431, 2021). "Gemcitabine causes BNIP3-related autophagy and leads to reduced lung cancer cell death, which may contribute to gemcitabine-acquired resistance." (PMID 33207677, 2020). "Inhibition of ERK5 abrogates the effects of MEK5 activity on the tumorigenicity of A549 lung cancer spheres through upregulation of the apoptosis-associated genes BCL2 interacting protein 3 (BNIP3) and BNIP3 like (BNIP3L), which play a critical role in cell death." (PMID 30901834, 2019). "CVB‐D can trigger mitophagy via the p65/BNIP3/LC3 axis in lung cancer cells, thereby inhibiting lung cancer." (PMID 40416597, 2025). "PINK1 and BNIP3 are both upregulated in lung cancer, while in ovarian cancer, PINK1 is downregulated, and BNIP3 is upregulated." (PMID 39765891, 2024). "Previous studies have reported that BNIP3 knockout mice exhibit increased tumorigenesis in breast and lung cancer models and are resistant to the cardiotoxicity of doxorubicin." (PMID 39454000, 2024). "Nuclear BNIP3 was also significantly correlated with a poor prognosis in non‐small cell lung cancer." (PMID 36200262, 2022). "For example, in ovarian cancer cells, cisplatin-induced cellular autophagy was dependent on BNIP3, and in the lung cancer cells, hypoxia augmented cisplatin-induced autophagy by suppressing the BNIP3 death pathway." (PMID 35219326, 2022). "We also took 4 pairs of human lung cancer tissues and their paraneoplastic tissues and extracted the proteins for western blot experiments, and the results showed that BNIP3 were upregulated in lung cancer tissue proteins." (PMID 36092153, 2022). "Altogether, these results suggest that CVB-D induced mitophagy in lung cancer cells by targeting the p65/BNIP3/LC3 pathway." (PMID 34072333, 2021). "In summary, we propose that treatment with CVB-D in lung cancer cells can provoke mitophagy through the p65/BNIP3/LC3 axis, and that this overactivated mitophagy is one of the contributing factors in apoptosis induction." (PMID 34072333, 2021). "To further explore the underlying mechanism involved in CVB-D-induced mitophagy, we first detected the expression of parkin/Pink1 and BNIP3/BNIP3L in lung cancer cells upon CVB-D treatment." (PMID 34072333, 2021). "In this review, we discuss the current data about BNIP3 involvement in lung cancer development and progression." (PMID 33207677, 2020). "Further study on SCLC will expand current knowledge concerning the development of different subtypes of lung cancer and, more precisely, the role of mitochondria and autophagy proteins, including BNIP3, in lung carcinogenesis." (PMID 33207677, 2020). "Mitochondria functioning and mitochondrial proteins, including BNIP3, have a strong impact on lung cancer development and progression." (PMID 33207677, 2020). "Cisplatin treatment increases BNIP3 protein levels; however, its combination with hypoxia reduced BNIP3 in lung cancer cell lines." (PMID 33207677, 2020). "Based on The Human Protein Atlas database, BNIP3 overexpression has been reported in up to 80% of patients with lung cancer." (PMID 33207677, 2020).